RGS2 (regulator of G protein signaling 2)
Diseases named in the same sentence as RGS2 in open-access papers (continued):
Sharing a sentence is not in itself a finding about the gene and the disease.
Obesity (8 papers, 2010 to 2024). Accumulation of substantial excess body fat. "On the one hand, RGS2 is associated with adipogenesis, obesity, and metabolic syndrome, and is also associated with insulin resistance by blocking insulin signal translation in adipocytes through interaction with the Gαq protein." (PMID 36497154, 2022). "Human and mouse studies have also implicated RGS2, 4 and 5, in the regulation of body weight and obesity." (PMID 22132185, 2011). "It is noteworthy that Akr1b8, Emr1, and Rgs2 are in the top 5% of genes testing causal for obesity traits in our database." (PMID 21179467, 2010). "Here, we show in colonic EECs, obesity was associated with an altered RGS profile, with differential expression patterns in colonic RGS2 (underexpression), RGS4 (underexpression), RGS9 (overexpression), and RGS12 (overexpression)." (PMID 39142076, 2024). "This study encourages further research exploring the role of RGS2 in preeclampsia and its short- and long-term comorbidities such as obesity, cardiovascular disease and anxiety disorders." (PMID 27558088, 2016). "Using this criteria RGS2, RGS4, RGS9, and RGS12 were identified as having physiologically relevant transcriptional alterations in obesity compared to lean." (PMID 39142076, 2024). "While the single-cell data set identified RGS2, RGS4, RGS9, and RGS12 as having physiologically relevant transcriptional alterations within EECs in obesity, this finding was only validated for RGS9 in the colon." (PMID 39142076, 2024). "In total, we identified a total of 3,298 differentially expressed genes, among which we discovered key genes such as UBD, RGS2, FASN, and SCD that have functions related to adipogenesis, body weight, obesity, and lipid metabolism." (PMID 38264212, 2023). "Colonic expression of RGS2, RGS4, and RGS12 in obesity was not significantly different compared to lean." (PMID 39142076, 2024).
bladder cancer (7 papers, 2021 to 2023). "Previous studies had explored the associations between RGS family members and bladder cancer risk, including RGS1, RGS2, RGS4, RGS5, RGS6, and RGS20." (PMID 34482807, 2021). "The knockdown of RGS2 markedly restored the abilities of migration and invasion in the ZHX3 knockdown bladder cancer cells." (PMID 37627900, 2023). "Bladder cancer patients with high ZHX3 and low RGS2 expression had the worst prognosis." (PMID 37627900, 2023). "In bladder cancer tissues, ZHX3 expression negatively correlated with RGS2 expression." (PMID 37627900, 2023). "Similarly, a promoter hypermethylation of G-protein signaling 2 (RGS2) gene by UHRF1 resulted in gene suppression and enhanced carcinogenesis in bladder cancer." (PMID 36077796, 2022). "In addition, another example can be explained in bladder cancer cells, where the multifunctional protein Ubiquitin-like with PHD and ring-finger domain 1 (UHRF1)-enhanced methylation status in RGS2 gene promoter repressed RGS2 expression but promoted cancer progression." (PMID 37118788, 2023).
depression (6 papers, 2018 to 2023). "Of note, the 3’ UTR single nucleotide polymorphism rs4606 in RGS2 was associated with post-traumatic stress disorder under conditions of lifetime exposure to a potentially traumatic event and low social support, suicidal ideation, and depressive disorders after childhood adversity." (PMID 34658840, 2021). "Consequently, silencing of RGS2 decreases oxidative stress injury and inflammation, but increases 5-HT concentration and cAMP pathway activity, thereby alleviating the cognitive impairment and neuronal damage in mice with depression-like behaviors." (PMID 37649067, 2023). "As related to depression, the RGS family members, RGS2, RGS4, RGS6 and RGS8 have all surfaced as being involved with regulating the manifestation of depression or play role as antidepressants through their capacity to activate different downstream molecular mechanisms." (PMID 34674723, 2021).
heart failure (6 papers, 2011 to 2025). Inability of the heart to pump blood at an adequate rate to meet tissue metabolic requirements. "Meanwhile, mice deficient in RGS2 exhibit increased susceptibility to heart failure." (PMID 40703433, 2025). "However, RGS2 expression declines in response to sustained stimulation and may exaggerate pathophysiological hypertrophy and the progression of heart failure." (PMID 38203580, 2023).
preeclampsia (6 papers, 2014 to 2025). Preeclampsia is a hypertensive disorder of pregnancy that is characterized by new-onset hypertension with proteinuria presenting after 20 weeks of gestation, and depending on mild or severe forms may initially present with severe headache, visual disturbances, and hyperreflexia. "Heterozygous knockout in the fetoplacental unit of mice caused key characteristics of the disorder including diastolic hypertension and proteinuria, suggesting a causative relationship between the loss of Rgs2 and preeclampsia symptoms." (PMID 41416997, 2025). "The rs4606 3′ UTR polymorphism of the Regulator of G-protein signaling 2 gene (RGS2) in the mother has been implicated in preeclampsia as well as in the development of chronic hypertension after preeclampsia." (PMID 27558088, 2016). "One of the genes implicated in blood pressure regulation, the regulator of G-protein signaling 2 gene (RGS2), has recently been suggested to be associated with preeclampsia and with the development of chronic hypertension after pregnancy." (PMID 27558088, 2016). "Furthermore, a single nucleotide polymorphism in the RGS2 3’ untranslated region, termed rs4606, is correlated with an increased risk for the development of preeclampsia in overweight women." (PMID 41416997, 2025). "Of the large family of RGS proteins, RGS2 is of particular importance in buffering this GPCR signaling associated with preeclampsia and is present in vascular cells, including endothelial cells, as well as many other cell types of the placenta, including trophoblasts, immune cells, and fibroblasts." (PMID 34831277, 2021). "The aim of this study was to investigate whether rs4606 in RGS2 is associated with preeclampsia in a Finnish case-control cohort, with specific focus on the potential impact of prepregnancy body mass index (BMI)." (PMID 27558088, 2016). "HDAC9 does not have an obvious role in the control of this particular GPCR pathway in preeclampsia except for its implications in the regulation of RGS2, which can also act on Gαi." (PMID 41416997, 2025). "RGS2 is a multifunctional regulator important for cardiac and smooth muscle function, neuronal plasticity, and preeclampsia." (PMID 38410462, 2024). "One study shows that a reduced expression of RGS2 within the placenta may contribute to the development of preeclampsia." (PMID 38974519, 2024). "We recently reported that women with a pregnancy complicated by preeclampsia differed in the genotype distribution of the rs4606 in RGS2, with a slightly higher proportion of women having either the CG or GG genotype, compared to women who never had a preeclamptic pregnancy." (PMID 24593135, 2014). "Our study suggests that the function of RGS2 could be one of the factors explaining the complex connection of preeclampsia and maternal overweight and warrants further investigation in other clinically well-characterized preeclampsia cohorts." (PMID 27558088, 2016).
colon cancer (5 papers, 2020 to 2025). "In this study, we primarily focused on analyzing the role of RGS2 in colon cancer–associated cellular phenotypes, particularly in terms of cell migration and the expression of cancer-related genes." (PMID 40754247, 2025). "In HCT116 colon cancer cells, RGS2 was shown to interact with GPR55, effectively suppressing GPR55-mediated oncogenic signaling." (PMID 40754247, 2025). "In this study, we elucidated the roles of S1P2 and S1P3, along with the function of RGS2, in colon cancer cells." (PMID 40754247, 2025). "Therefore, further investigations into aspects beyond cell migration are warranted to fully elucidate the role of RGS2 in colon cancer." (PMID 40754247, 2025). "Finally, we evaluated whether RGS2 expression affects S1P2- and S1P3-mediated cancer–associated cellular phenotypes by assessing cell migration and the expression of cancer-related genes in HCT116 colon cancer cells." (PMID 40754247, 2025). "Both RGS2 and RGS4 abolished PAR4-activated ERK phosphorylation, calcium mobilization and RhoA activity, as well as PAR4-mediated colon cancer cell proliferation and related gene expression." (PMID 32517689, 2020). "RGS2 has been shown to suppress oncogenic signaling by inhibiting the phosphorylation of ERK and AKT This mechanism is particularly evident in colon tumors, where ERK and AKT phosphorylation are critical regulatory events driving malignant transformation and cancer cell behavior." (PMID 40754247, 2025).
colorectal cancer (5 papers, 2022 to 2025). A primary or metastatic malignant neoplasm that affects the colon or rectum. "Similarly, RGS2 was shown to be up-regulated in the patients with early onset colorectal cancer." (PMID 35642021, 2022).
metabolic syndrome (5 papers, 2010 to 2022). A cluster of metabolic risk factors for CARDIOVASCULAR DISEASES and TYPE 2 DIABETES MELLITUS. "The RGS2 gene is located in a region on chromosome 1 (chr1.11:192,809,039–192,812,275) that is associated with body fat distribution and metabolic syndrome in men." (PMID 36497154, 2022). "Together, this evidence implicates RGS2 as a candidate in developing metabolic syndrome and its associated factors in T2DM." (PMID 33562475, 2021). "More recently, RGS2 variation has been associated with metabolic syndrome and weight gain in humans." (PMID 21179467, 2010). "Furthermore, in agreement with our results and with the idea that RGS2 induces insulin resistance, it has been reported that those mutations resulting in increased RGS2 expression levels have been associated with metabolic syndrome and insulin resistance." (PMID 33562475, 2021). "Interestingly, another study found that the C to G substitution at position −391 in the RGS2 promoter increases RGS2 expression in adipocytes and is associated with metabolic syndrome in white European men." (PMID 33562475, 2021). "Interestingly the −391 C to G substitution in the promoter of RGS2 has been associated with metabolic syndrome in white European men and the rs4606 CG or GG genotypes have been found to predict weight gain in young hypertensive men." (PMID 27558088, 2016). "Interestingly, a mutation in the Rgs2 promoter that increases Rgs2 expression has been shown to enhance susceptibility to metabolic syndrome in humans." (PMID 25161195, 2014).
non-small cell lung carcinoma (5 papers, 2022 to 2024). A group of at least three distinct histological types of lung cancer, including non-small cell squamous cell carcinoma, adenocarcinoma, and large cell carcinoma. "Up-regulation of RGS2 expression resulted in a biomarker of delayed value-added and poor prognosis in non-small cell lung cancer, relieving the dormancy of slow-cycling/dormant cancer cells after surgery/chemotherapy and causing tumor recurrence." (PMID 38274323, 2024). "Recent studies in different cell systems showed that RGS2 attenuates G protein signaling in chemo-resistant non-small cell lung cancer cell lines, but promotes AKT phosphorylation in human prostate adenocarcinoma cell line LNCaP cells." (PMID 38410462, 2024). "Increased levels of regulator of G protein signaling 2 (RGS2) activated by chemotherapy-induced-ER stress have been identified in models of slow cycling/dormant cancer cells from non-small cell lung cancer cell lines and Patient-Derived Xenografts." (PMID 37207158, 2023). "RGS2 has been confirmed to regulate a dormant state in non-small cell lung cancer (NSCLC)." (PMID 35462906, 2022). "The regulator of G protein signaling 2 (RGS2) promotes dormancy and the survival of dormant cells in non-small-cell lung cancer, and its depletion led to apoptosis in these cells." (PMID 39682769, 2024).
Parkinsonism (5 papers, 2012 to 2024). Characteristic neurologic anomaly resulting from degeneration of dopamine-generating cells in the substantia nigra, a region of the midbrain, characterized clinically by shaking, rigidity, slowness of movement and difficulty with walking and gait. "Moreover, associations between RGS2 polymorphisms and antipsychotic-induced Parkinsonism have been evidenced." (PMID 34658840, 2021). "RGS2 has previously been identified as a modulator of LRRK239 expression, a gene known to be a genetic cause of Parkinson’s Disease." (PMID 31797917, 2019).
pulmonary fibrosis (5 papers, 2016 to 2023). Chronic progressive interstitial lung disorder characterized by the replacement of the lung tissue by connective tissue, leading to progressive dyspnea, respiratory failure, or right heart failure. "Pirfenidone treatment or direct overexpression of recombinant RGS2 in human lung fibroblasts inhibited the profibrotic effects of thrombin, whereas loss of RGS2 exacerbated bleomycin-induced pulmonary fibrosis and mortality in mice." (PMID 27549302, 2016). "Altogether, our study indicates that endogenous RGS2 itself plays a protective role and that loss of RGS2 augments the development of pulmonary fibrosis." (PMID 27549302, 2016). "Enhanced RGS2 expression protects against pulmonary fibrosis in mice, while knockdown of RGS2 promotes fibrosis in mice, which demonstrates that endogenous RGS2 has an antifibrotic function and that RGS2 is the basis of the antifibrotic effect of PFD." (PMID 36182915, 2022). "Its effect on attenuating bleomycin-induced pulmonary fibrosis in mice is related to the increase of RGS2." (PMID 36182915, 2022). "The effect of PFD (8 mM) on the expression of RGS2 and lung fibrosis markers in MFBs was explored after co-culture of hUC-MSCs with MFBs." (PMID 36182915, 2022). "In contrast to RGS5 knockout, RGS2-/- mice displayed increased acute inflammation upon house dust mite and LPS inoculation and an augmented development of pulmonary fibrosis." (PMID 34502263, 2021). "Pirfenidone prevents collagen I fibril formation, and up regulates RGS2 which can potentially lead to amelioration of pulmonary fibrosis." (PMID 33585519, 2020). "Scoring the bleomycin-induced histological fibrosis by the Ashcroft method confirmed that pulmonary fibrosis was significantly increased in RGS2−/− mice as compared with RGS2+/+ mice (4.80 ± 0.15 vs. 3.53 ± 0.14, n = 5, p < 0.01)." (PMID 27549302, 2016). "However, the biological function of RGS2 in bleomycin-induced pulmonary fibrosis in mice and its mechanism of action are rarely reported in the literature." (PMID 36182915, 2022). "It has been reported that overexpression of RGS2 significantly reduces the expression of fibrosis markers and thus plays a protective role against pulmonary fibrosis, this result that could support our hypothesis." (PMID 36182915, 2022). "Thus, the elevated RGS2 expression induced by PFD treatment is crucial for PFD protection of mice against bleomycin-induced pulmonary fibrosis." (PMID 27549302, 2016). "Using cellular and animal models, we demonstrate here that endogenous RGS2 exhibits anti-fibrotic functions and that early upregulation of RGS2 contributes to PFD amelioration of pulmonary fibrosis." (PMID 27549302, 2016). "Previous studies suggested that RGS2, RGS4 and RGS5 were protective against airway-hyperresponsiveness with modulated airway or bronchial contractility, while RGS2 was protective against bleomycin-induced lung fibrosis." (PMID 34502263, 2021). "Pirfenidone treatment reduced bleomycin-induced pulmonary fibrosis in wild-type but not RGS2 knockout mice." (PMID 27549302, 2016). "This induction of RGS2 expression is a previously unrecognized genomic response to PFD, and our further studies strongly suggest that RGS2 upregulation is a significant contributor to the pulmonary fibrosis protection induced by PFD." (PMID 27549302, 2016). "Treatment with pirfenidone significantly increased RGS2 mRNA and protein expression in both a human fetal lung fibroblast cell line and primary pulmonary fibroblasts isolated from patients without or with idiopathic pulmonary fibrosis." (PMID 27549302, 2016). "Interestingly, RGS2 has been reported to be increased in IPF patient samples, which is consistent with the notion that upregulated RGS2 functions as a potential feed-back regulator of pulmonary fibrosis." (PMID 27549302, 2016).
mild cognitive impairment (4 papers, 2016 to 2025). "Besides, it is reported that 5-HT receptors are underlying targets for treatment of cognitive impairment in senescence, and consistently, activity of cAMP pathway is elevated upon silencing of RGS2." (PMID 37649067, 2023). "In contrast, down-regulation of Rgs2 relieved mouse cognitive impairment, and consistently, siRNA-mediated knockdown of Rgs2 reinforced the 5-hydroxytryptamine (5-HT) levels in hippocampal CA1 neurons." (PMID 37649067, 2023). "Lower RGS2 expression levels were also discovered in published expression data sets from postmortem AD brain tissues as well as in mild cognitive impairment and AD blood samples compared with controls." (PMID 27701409, 2016). "For instance, reduced expression of RGS2 may be related to the occurrence of mild cognitive impairment." (PMID 40703433, 2025). "In this study, we compared RGS2 mRNA levels in peripheral blood samples from 69 mild cognitive impairment (MCI) patients to 50 age- and sex-matched non-cognitively impaired controls, out of which 25 patients were monitored at 1 year." (PMID 34658840, 2021).
Alzheimer disease (3 papers, 2013 to 2021). A progressive, neurodegenerative disease characterized by loss of function and death of nerve cells in several areas of the brain leading to loss of cognitive function such as memory and language. "Microarray data from large datasets suggested reduced RGS2 mRNA levels in the post-mortem brain tissue and blood of Alzheimer’s disease (AD) patients." (PMID 34658840, 2021). "Moreover, a significant correlation (R=0.560; P=0.006) was observed between RGS2 expression levels and ADAS (Alzheimer's Disease Assessment Scale) scores." (PMID 27701409, 2016).
anxiety disorder (3 papers, 2012 to 2021). A category of psychiatric disorders which are characterized by anxious feelings or fear often accompanied by physical symptoms associated with anxiety. "In the brain, both clinical and animal models showed that lower RGS2 expression is associated with anxiety disorders." (PMID 23285140, 2012).
Arrhythmia (3 papers, 2021 to 2025). Any cardiac rhythm other than the normal sinus rhythm. "In our previous study, we showed the beneficial effect of Gαq-RGS2 signaling inhibitor in the aminophylline induced cardiac arrhythmia." (PMID 34311782, 2021). "These doses in subacute toxicity were selected from the effective dose (10 mg/kg) of Gαq-RGS2 signaling inhibitor against the cardiac arrhythmia in the rats in our previous study." (PMID 34311782, 2021). "We previously reported that male Rgs2/5 dbKO mice, unlike their female counterparts, display left ventricular dilation at baseline and developed arrhythmias related to increased Gi/o activity." (PMID 39746869, 2025).